EGFR (epidermal growth factor receptor)
Diseases named in the same sentence as EGFR in open-access papers (continued):
Sharing a sentence is not in itself a finding about the gene and the disease.
adenocarcinoma (continued). "Mutations in EGFR tyrosine kinase are observed in 51.4% of advanced NSCLC adenocarcinoma cases in Asian populations compared, with approximately 20% among the white population." (PMID 32762742, 2020). "Adenocarcinomas have more EGFR mutations than do SCCs, and thus there are more options for targeted therapy, as compared to SCCs." (PMID 33251387, 2020). "Recurrence after definitive management in early or locally advanced adenocarcinoma occurred in 32 EGFR-mutated cases and 29 EGFR-wildtype cases." (PMID 32523650, 2020). "Analysis of oncogenic driver mutations was performed in 35 patients (70% of patients with adenocarcinoma), 3 (9%) had a mutation in the EGFR gene." (PMID 32517716, 2020). "In this study, all were Japanese patients with activating EGFR mutations, and all but one (97.8%) had adenocarcinoma and 43 of 45 (95.6%) had distant metastases." (PMID 31217900, 2019). "Of the 169 EGFR-mutation positive adenocarcinomas, 64 adenocarcinoma specimens were randomly selected and sequenced with MBS." (PMID 30808329, 2019). "Of these patients, 216 patients had adenocarcinoma, and 144 (56.3%) of them were documented to have EGFR mutation." (PMID 31415376, 2019). "So we conducted this study to compare the effectiveness of gefitinib, erlotinib, and afatinib in advance stage adenocarcinoma NSCLC patients with EGFR mutations in the Indonesian population." (PMID 31526459, 2019). "One of the most known and important mutations in NSCLC, especially adenocarcinoma, is epidermal growth factor receptor (EGFR) gene mutations." (PMID 31870098, 2019). "This process was first described in 2006 in a patient originally diagnosed with adenocarcinoma revealing SCLC with the original EGFR exon 19 deletion mutation in a repeat biopsy." (PMID 35582592, 2019). "The successful development of molecular targeting agents that inhibit growth signals from driver mutations has improved the treatment outcome of adenocarcinoma patients with EGFR mutations." (PMID 30808329, 2019). "A recent Korean study of 57 patients with adenocarcinoma harboring activating EGFR mutations found that bone metastasis was the only independent factor predicting ctDNA detection." (PMID 31652678, 2019). "We performed EGFR mutation analysis using adenocarcinoma cells from the pleural effusion and detected exon 19 deletion and exon 20 T790 M mutation; therefore, osimertinib was substituted for erlotinib." (PMID 30681568, 2019). "Despite of the small sample size of this cohort (n = 40), the mutation profiles identified support previous findings that the majority of adenocarcinomas associated mutations occur in EGFR exon 19 and 21 and that KRAS and EGFR mutations are mutually exclusive." (PMID 31841547, 2019). "The survival prediction models can be used to make individualized predictions with different EGFR mutation status and a useful tool for selecting regimens for treating advanced adenocarcinoma." (PMID 31419239, 2019). "In this study, ROC curves comparing the diagnostic performance of the GGO volume percentage values showed an area under the curve value of 0.783, which demonstrated good validity for the diagnosis of adenocarcinomas with EGFR mutation." (PMID 30956990, 2019). "The patients we included in our study were relatively young, predominantly non‐smoking female, and primarily adenocarcinoma histology, which is a population with a high probability of harboring EGFR mutations and the dominant population for EGFR‐TKI treatment." (PMID 30993909, 2019). "We also identified six DMPs significantly associated with EGFR mutation in patients with adenocarcinoma." (PMID 31450665, 2019). "Most of the adenocarcinoma subtypes have EGFR mutations, and EGFR-tyrosine kinase inhibitors (EGFR-TKIs) are the preferred treatment choice for this type of patients." (PMID 31874677, 2019).
adenocarcinoma (continued). "Robust data exist regarding the prevalence of EGFR mutations in adenocarcinoma patients, ranging from the highest EGFR mutation frequency of 47% in the Asia-Pacific subgroup to the lowest frequency of 12% in the Oceania subgroup." (PMID 31976327, 2019). "In the adenocarcinoma subtype, activating mutation in the epidermal growth factor receptor (EGFR) gene occurs in approximately 50% of Asian patients and 10–15% of Caucasians." (PMID 31554160, 2019). "Adenocarcinoma patients with EGFR mutations (29.8%) showed a trend towards shorter TTR (p = 0.09) and OS (p = 0.09)." (PMID 30819158, 2019). "D’Incecco and colleagues confirmed the Azuma preclinical data, demonstrating a significant correlation between PD-L1 expression and the adenocarcinoma subtype and EGFR mutations." (PMID 31554160, 2019). "All three patients with inconsistent EGFR mutational results were pathologically diagnosed with adenocarcinomas." (PMID 30807604, 2019). "For example, 10/23 (43.5%) adenocarcinoma LCs harbored pathogenic mutations in EGFR (8/10 in exon 19 and 2/10 in exon 21)." (PMID 30925779, 2019). "EGFR mutant NSCLC was reported to carry a mean of 4.5 mutations/megabase (Mb) as compared with 9.1 in NSCLC adenocarcinoma." (PMID 30857358, 2019). "The aim of the study is to develop and validate a novel nomogram, incorporating epidermal growth factor receptor mutation status and treatments, for predicting 1-year and 2-year survival probability of patients with advanced adenocarcinoma." (PMID 31419239, 2019). "EGFR-IHC and mutational analysis were performed in 61/104 adenocarcinomas, with available specimens." (PMID 31817278, 2019). "Overall, regarding clinical and histopathological characteristics, adenocarcinoma solid subtype was strongly associated with worse disease outcome in a multivariate analysis irrespective the presence of EGFR mutations." (PMID 30824880, 2019). "Patients who received MTs with supportive care had more adenocarcinoma (p < 0.0001) or harbored more EGFR mutations (p < 0.0001) than those in the BSC alone group." (PMID 31882700, 2019). "In a systematic review of 151 studies, the overall frequency of somatic EGFR mutations in NSCLC patients with adenocarcinoma histology is approximately 22% in North America (Range: 3%-42%)." (PMID 31581267, 2019). "The most recurrently EGFR mutation in the present adenocarcinoma series was a deletion in exon 19 followed by a substitution in exon 21 (p.L858R), similarly to previously reported in Brazilian patients." (PMID 30824880, 2019). "EGFR mutation occurred in Asian population in 47.9% of adenocarcinoma cases, while in Western population in 19.2%." (PMID 31867335, 2019). "Three human adenocarcinoma cell lines with mutated EGFR (HCC827, H1975 and H1650) and one with wild-type EGFR (A549) were xenografted on 35 Nude mice." (PMID 30612556, 2019). "The differences rate of EGFR mutations were associated with patients’ sex (p = 0.02), adenocarcinoma (p < 0.01), TNM stage (p < 0.01), and brain metastasis (p < 0.01)." (PMID 30337598, 2018). "Most patients with EGFR sensitizing mutations and who respond to EGFR-TKIs present with adenocarcinoma." (PMID 29435191, 2018). "Mutations and amplification of EGFR are closely associated with each other, and EGFR amplification occurs only in EGFR-mutated adenocarcinoma." (PMID 29690599, 2018). "Our results was different from the previous studies since we focused only on the patients with only EGFR mutation-positive adenocarcinoma." (PMID 30055587, 2018). "While adenocarcinoma usually presents at the lung periphery and is frequently associated with an initial malignant pleural effusion, a positive association between EGFR mutation and the presence of malignant pleural effusion has been reported." (PMID 29435191, 2018).
adenocarcinoma (continued). "The most prevalent subset of adenocarcinoma, including EGFR-mutated adenocarcinoma, appears to develop from AAH to AIS, to MIA, to overt invasive adenocarcinoma with a lepidic pattern, which is typically observed in TRU-type adenocarcinoma." (PMID 29690599, 2018). "Of all patients, 95% (38/40) had adenocarcinoma, 75.0% (30/40) had stage IV disease, and 57.5% (23/40) had EGFR mutations." (PMID 30526545, 2018). "Among all patients with adenocarcinoma, 10% had an epidermal growth factor receptor mutation and 3% had the echinoderm microtubule-associated protein-like 4–anaplastic lymphoma kinase (EML4-ALK) fusion gene." (PMID 29442281, 2018). "Regarding the association between having the EGFR mutation and adenocarcinoma versus other histological subtypes, we determined an odds ratio of 0.73 in adenocarcinomas versus other subtypes (95% CI, 0.47–1.12)." (PMID 30217176, 2018). "EGFR inhibitors are the current standard of care for adenocarcinoma patients with EGFR activating mutations." (PMID 30119639, 2018). "Conversely, EGFR-targeted therapies show promise in a subset of adenocarcinomas with EGFR activating mutations." (PMID 29937990, 2018). "For adenocarcinomas containing EGFR mutations, EGFR amplification is involved in the transition from AIS to MIA." (PMID 29690599, 2018). "Three cells with highest DNA quality (GII4) were selected for targeted sequencing of EGFR Exon 21 and we identified an EGFR-L858R missense mutation that is common in adenocarcinoma of NSCLC in two out of three DCCs." (PMID 29721166, 2018). "We observed mainly the acinar type (54.3%) in EGFR mutation-positive adenocarcinoma and the proportion of solid type increased in the ever- smoker." (PMID 30055587, 2018). "In 5 of the 6 studies reporting EGFR mutation status according to the histological subtype, there was a higher frequency of EGFR mutation in adenocarcinomas compared with other subtypes: (13 vs 0%, 40.6 vs 31.3%, 25 vs 0%, 32.46 vs 10.25% and 36.25 vs 15,38%)." (PMID 30217176, 2018). "There were also fewer women than men, as female patients mostly have adenocarcinoma pathology with EGFR mutations; most of these patients need to take only oral targeted drugs outside the hospital and do not need to be hospitalized." (PMID 30257820, 2018). "Owing to the higher prevalence of EGFR mutations, TKIs have shown a dramatic efficacy in patients with adenocarcinoma." (PMID 32922870, 2018). "Ninety-five percent of EGFR mutations are found in adenocarcinomas, which are the most common histologic type of NSCLC." (PMID 28988295, 2018). "A 62-year-old Asian male never smoker who presented with stage IV EGFR L858R-positive adenocarcinoma developed EGFR T790 M mutation after 14 months of treatment with erlotinib combined with thoracic radiotherapy as first-line therapy." (PMID 30400855, 2018). "Recurring mutations have been reported in genes coding for epidermal growth factor receptors (EGFR) in 10–40% of adenocarcinomas, but these mutations are rare in squamous tumors." (PMID 29587656, 2018). "Transformation from EGFR-mutated adenocarcinoma to SCLC occurs in 5% of patients with acquired resistance to EGFR-TKIs." (PMID 30445769, 2018). "As EGFR-mutated adenocarcinomas frequently develop via the presumed multistep continuum, incidence rates of AAH, AIS, and MIA are high in East-Asian populations." (PMID 29690599, 2018). "In the stepwise development of EGFR-mutated adenocarcinoma, EGFR amplification plays a crucial role in the progression to invasive adenocarcinoma." (PMID 29690599, 2018). "In human adenocarcinomas the frequency of EGFR mutations is estimated between 15 and 45%, whereas KRAS mutation was detected in 20% of the cases depending on the geographical region." (PMID 29415661, 2018).
adenocarcinoma (continued). "EGFR‐TKIs had been proven to offer prolonged progression‐free survival (PFS) and better life quality than chemotherapy in advanced NSCLC patients with EGFR mutations in many clinical trials, in which most of the patients were adenocarcinoma." (PMID 30109777, 2018). "Chemotherapy with etoposide and carboplatin was reported to be effective in two cases of SCLC transformation from EGFR-mutated adenocarcinoma." (PMID 30445769, 2018). "In agreement with the literature, EGFR mutations in LC patients were detected in former smoker women diagnosed with adenocarcinoma at a frequency of 28%." (PMID 29854313, 2018). "The non-small-cell lung cancer (NSCLC) subtype, accounting for the majority of the cases, includes adenocarcinoma and is often treated with tyrosine kinase inhibitors targeting epidermal growth factor receptor (EGFR)-activating mutations." (PMID 29600194, 2018). "In our current study, the patients with adenocarcinoma harboring a single sensitizing uncommon mutation had a fine initial treatment response to first-line EGFR TKIs (disease control rate of 85%), PFS (median, 7.7 months), and OS (median, 18.4 months)." (PMID 30428509, 2018). "We performed digital PCR analysis of cfDNA from four patients diagnosed with adenocarcinoma bearing the EGFR L858R mutation (n = 2) or EGFR exon 19 deletion (n = 2)." (PMID 29721209, 2018). "It seemed that female patients who had IIIb-IV stage adenocarcinoma and brain metastasis were associated with high likelihood of EGFR mutations." (PMID 30337598, 2018). "The most common driver mutations associated with adenocarcinoma are epidermal growth factor receptor (EGFR) mutations (Midha, Dearden, & McCormack, 2015)." (PMID 29900027, 2017). "We observed a statistically significantly higher EGFR mutation prevalence in adenocarcinomas (p<0.001)." (PMID 28832323, 2017). "And some studies also revealed the relationship between TTF-1 expression and gene mutations that a higher epidermal growth factor receptor (EGFR) mutation rate would be found in TTF-1 positive adenocarcinoma." (PMID 29296178, 2017). "Several studies have indicated a therapeutic benefit of EGFR-TKIs in adenocarcinomas harboring an EGFR mutation." (PMID 29312580, 2017). "STAT3 is persistently activated in about 50% of NSCLCs, especially in adenocarcinomas harboring activating mutations in EGFR which activate the gp130/JAK/STAT3 pathway by means of IL-6 upregulation." (PMID 27835873, 2017). "In China, testing for EGFR gene mutations is recommended before treating advanced NSCLC and is considered essential for patients with adenocarcinoma given the high rate of EGFR gene mutations in East Asian patients." (PMID 28673332, 2017). "The patient in Case 1 was a 72-year-old female non-smoker who was initially diagnosed with T2aN2M0, stage IIIA adenocarcinoma harboring an EGFR exon 21 L858R mutation." (PMID 29169381, 2017). "Several genes associated with glucose metabolism and the cell cycle were specifically down-regulated in EGFR-mutated adenocarcinomas." (PMID 28422979, 2017). "Comprehensively investigate the association of CT morphology and clinical findings of adenocarcinoma with EGFR mutation status." (PMID 28949965, 2017). "A similar increase in FGFR1 expression was observed in the EGFR-mutated NSCLC adenocarcinoma cell line PC-9 during development of erlotinib resistance (data not shown)." (PMID 28368392, 2017). "Over the past decade several oncogenic drivers have been identified, though most distinct are the observations of activating mutations in the epidermal growth factor receptor (EGFR) of patients with adenocarcinoma histology." (PMID 28978110, 2017). "This is in marked contrast to NSCLC, particularly adenocarcinoma, where genome sequencing efforts have revealed the identity of numerous recurrent, actionable somatic alterations, including oncogenic EGFR mutations, as well as ALK- and ROS1 rearrangements." (PMID 29138515, 2017).
adenocarcinoma (continued). "Advanced NSCLC patients, especially ones with adenocarcinoma histology and EGFR active mutations, show great clinical benefits from EGFR-TKIs6." (PMID 29259263, 2017). "Among 27 adenocarcinoma patients, eight harbored EGFR mutations, including L858R at Exon21 (n = 3), Exon19 deletion (n = 4), and Exon 20 insertion (n = 1)." (PMID 29152077, 2017). "In patients with EGFR-activating mutations, Cox analysis showed that patients with adenocarcinoma, recurrent disease, or EGFR-TKI treatment had significantly longer survival." (PMID 28079142, 2017). "Another study has further demonstrated that CEA is associated with EGFR mutation in adenocarcinomas." (PMID 28877268, 2017). "As a therapeutic target, mutations in EGFR are major genetic variants in adenocarcinoma, and it is known that adenocarcinomas with EGFR mutations can transform to SCLC after EGFR-TKI treatment." (PMID 29312580, 2017). "Subgroup analysis suggested although the overall mutation rate is different in tissue, plasma and adenocarcinoma subgroups, the relationship between EGFR mutations and clinicopathological parameters was similar." (PMID 28107191, 2017). "In this study, we investigated parallel resistance mechanisms acquired by HCC827, an EGFR-mutated adenocarcinoma cell line dependent on EGFR activity and sensitive to erlotinib." (PMID 28368392, 2017). "Adenocarcinoma was the most common type of histology, consisting of 88.8%, and EGFR mutation was detected in 49.0% of patients." (PMID 29113396, 2017). "In multivariable analysis, compared to other histologies, adenocarcinoma was associated with borderline higher incidence of EGFR mutation, with crude OR of 3.8 (p = 0.02) while adjusted OR of 4.9 but only approaching statistical significance (p = 0.06)." (PMID 29232915, 2017). "Among the histologic types, adenocarcinoma was associated with a significantly higher incidence of EGFR mutation on univariate analysis (p = 0.02)." (PMID 29232915, 2017). "Active EGFR mutations are often observed in female patients or in patients with adenocarcinoma and have been reported as a favorable prognostic factor in patients with NSCLC." (PMID 28915677, 2017). "EGFR inhibitors, such as erlotinib and gefitinib, are of significant benefit in EGFR mutation-positive malignancies, which are primarily adenocarcinomas." (PMID 27444682, 2017). "All cases were, pathologically, adenocarcinomas, except for one pleomorphic carcinoma, and all were EGFR-mutation positive." (PMID 29212495, 2017). "We consecutively included NSCLC patients who underwent surgical resection, and thus, most had adenocarcinoma with single or few metastases and EGFR mutations." (PMID 29152077, 2017). "In the present study, we enrolled 11,678 Taiwanese patients with a pure adenocarcinoma histology, advanced stage disease, detailed smoking data, and known EGFR mutation status." (PMID 29228697, 2017). "EGFR-mutated adenocarcinomas are biologically indolent with potentially lower levels of glucose metabolism than wild-type tumors." (PMID 28422979, 2017). "EGFR gene mutations were diagnosed in 7 adenocarcinoma patients (14,6% of all patients, 6 female, 1 male, median age: 64 years, 5 non-smokers, one current and one former smoker)." (PMID 28969070, 2017). "We found a higher EGFR mutation frequency in women, the adenocarcinoma histological subtype and the elderly population." (PMID 28832323, 2017). "Mutations in epidermal growth factor receptor (EGFR) or rearrangements in the anaplastic lymphoma kinase (ALK) gene are the most common findings—almost 25% of adenocarcinoma cases." (PMID 28430151, 2017). "Pellino-1 overexpression was significantly higher in patients with adenocarcinoma harboring EGFR mutation, increased EGFR gene copy numbers and MET expression." (PMID 28009353, 2017).